FOXP3 (forkhead box P3)
Diseases named in the same sentence as FOXP3 in open-access papers (continued):
Sharing a sentence is not in itself a finding about the gene and the disease.
colitis (continued). "A mouse strain, in which tdTomato and enhanced green fluorescent protein were under the control of the Foxp3 promoter and Il17a promoter, was established and subjected to colitis induction with dextran sulfate sodium." (PMID 38415949, 2024). "Further, DIM has been reported to ameliorate the severity of DSS-induced colitis through AhR-dependent regulation of the T-helper 17 (Th17)/Foxp3+ Regulatory T-cell (Tregs) axis, favoring the suppression of pro-inflammatory Th17 activity." (PMID 39337636, 2024). "Exogenous addition of butyrate enhances histone H3 acetylation in the promoter and conserved non-coding sequence regions of the Foxp3 locus, induces differentiation of mouse colonic T-cells and ameliorates the development of colitis." (PMID 37869005, 2023). "In a previous study, we showed that SMILE expression inhibits inflammatory bowel disease (IBD) in a mouse model of colitis via the regulation of Foxp3 expression." (PMID 37143079, 2023). "In light of this, experimental colitis models have indicated that Foxp3+ Tregs have anti-inflammatory functions in the intestine by suppressing Th17 responses and thus reducing Th17/Treg ratio." (PMID 36707899, 2023). "Taken together, these data indicate that in conditions of impaired Foxp3+ IL-10 production, intestinal Tr1 cells expand in frequency and function to provide functional immune suppression and protect against spontaneous colitis." (PMID 37314833, 2023). "We showed that larval E. multilocularis infection in the peritoneal cavity attenuated colitis in Balb/c mice and induced a significant expansion of colonic Foxp3+ Treg populations." (PMID 37355675, 2023). "To determine the requirement of Foxp3+ Treg-specific IL-10 for protection against colitis, we generated Foxp3-specific IL-10 knockout (KO) mice (IL-10 conditional KO [cKO] mice)." (PMID 37314833, 2023). "Within the adaptive arm of the immune response, transfer colitis studies have also attested to the importance of colonic Foxp3+ Tregs and to novel regulatory CD8 T cells in helminthic regulation of IBD in mice." (PMID 37189818, 2023). "These SCFA-producing bacterial strains play a crucial role in maintaining the population of colonic Foxp3+ Tregs for the protection against colitis." (PMID 38107848, 2023). "AT-MSC-secreted PGE2 also attenuated inflammation by enhancing Foxp3 + Tregs numbers in DSS-induced mice colitis." (PMID 36707899, 2023). "A study found that IL-33 promoted Th2 and Treg cell responses to ameliorate colitis induced by trinitrobenzene sulfonic acid (TNBS) in mice in a Foxp3-dependent form." (PMID 37153553, 2023). "Protection from colitis in IL-10cKO mice was associated with an expanded population of IL-10–producing type 1 Tregs (Tr1, CD4+Foxp3−) in the colonic lamina propria that produced more IL-10 on a per-cell basis compared with wild-type intestinal Tr1 cells." (PMID 37314833, 2023). "Collectively, our findings reveal a role for Tr1 cells in the gut, as they expand to fill a tolerogenic niche in conditions of suboptimal Foxp3+ Treg-mediated suppression and provide functional protection against experimental colitis." (PMID 37314833, 2023). "More specifically, A. muciniphila supplementation has been proven beneficial against CD4 T cell transfer model of colitis in animals through the upregulation of RORγt+Foxp3+ T regulatory 17 cells." (PMID 38107848, 2023). "Another group reported that PGE2 secreted by feline adipose tissue-derived MSCs reduced inflammation by increasing FOXP3+ Treg in an in vivo mouse model of colitis." (PMID 36830980, 2023). "As expected, PBS- or Foxp3– Tconv-infused mice showed severe thyroiditis, splenitis, pneumonitis, dermatitis, hepatitis, pancreatitis, gastritis, and colitis." (PMID 38099494, 2023). "To better understand the role of Foxp3-specific IL-10 in protecting against colitis, we tracked changes in body weight among Foxp3-specific IL-10cKO mice during a 30-wk time course." (PMID 37314833, 2023).
colitis (continued). "Foxp3 is involved in the development of Treg cells that secrete IL-10 to inhibit inflammation, and DSS-induced colitis results in a decrease in Foxp3+Treg cells." (PMID 35237276, 2022). "For instance, IL-10+FOXP3- splenic Tr1 cells are less protective against colitis development in contrast to their intestinal counterparts." (PMID 36389662, 2022). "H. hepaticus strongly induces cognate Ag-specific RORγt+ Foxp3- Th17 responses in IL-10-/- mice or mice treated with IL-10 blockades, thereby inducing the experimental colitis." (PMID 36310871, 2022). "On the contrary, the expression of anti-inflammatory factors IL-4, IL-10, TGF-β and Foxp3 were significantly declined in the colitis group compared to the healthy mice." (PMID 35372817, 2022). "Instead, they rather seem closest to mouse RORγt+/FoxP3+ gut Tregs, demonstrated to protect against colitis." (PMID 36479125, 2022). "Recently, Odoribacter splanchnicus has been reported to induce the development of immune-suppressive intestinal Th17 cells and Foxp3+/RORγt+ regulatory T cells, both of which limit colitis development in mouse models." (PMID 35967333, 2022). "During co-housing with NOD2−/− mice, acquisition of Rickenellaceae by wild-type mice was associated with increased proportions of CD4+LAP+Foxp3− T cells and less severe TNBS-colitis." (PMID 36012618, 2022). "FoxP3+RORγt+ cells retain suppressive function and are more suppressive than FoxP3+RORγt− cells in a T cell transfer colitis model." (PMID 35309306, 2022). "Such imprinting was shown to partly depend on the induction, by Clostridium IV and XIVa members, of mouse RORγt-expressing FoxP3+ Tregs, which prevent colitis and limit Th2-mediated responses such as allergic diseases." (PMID 36479125, 2022). "Therefore, we decided to examine whether MLN CD25+CD4+ T cells from DSS-treated Yeti/CD1d KO mice (mostly Foxp3− populations) can increase susceptibility to DSS-induced colitis compared to CD25+CD4+ T cells (primarily Foxp3+ populations) from DSS-treated CD1d KO mice." (PMID 36499642, 2022). "Heat-killed Lacticaseibacillus casei Lbs2 lessened the histopathological features of colitis mice by increasing the frequency of FoxP3+ regulatory T cells in mesenteric lymph nodes." (PMID 36558391, 2022). "In the present study, during DSS-induced colitis, immune suppressive FoxP3+CD25+ Tregs within colonic LP were markedly increased in mPGES-1−/− mice compared with WT mice." (PMID 34983695, 2022). "Polysaccharide A of B. fragilis mediates the conversion of CD4+ T cells into Foxp3+ Treg cells and is capable of reversing experimental colitis in mice." (PMID 36584066, 2022). "In a colitis model, ICOS deficiency resulted in an increased induction of IL-10 in CD4 T cells but reduced accumulation of Foxp3+ cells in large intestine." (PMID 36591244, 2022). "We next examined the effect of mPGES-1 genetic deletion on the population of FoxP3+CD25+ Tregs in LPMCs isolated from colons with DSS-induced colitis." (PMID 34983695, 2022). "In vivo, Foxp3-specific knockout of CREB prevents colitis in a T cell mediated transfer colitis model in an IL-10 dependent way however aggravates disease activity in a murine lupus and asthma model." (PMID 36096831, 2022). "In the DSS-induced colitis model, HDAC inhibitor can increase the expression of the Foxp3 gene and improve the inhibitory function of regulatory T cells in mice with colitis, thus alleviating the inflammation phenotype." (PMID 35173618, 2022). "For example, Salvia miltiorrhiza (Danshen) enhances the expression of forkhead box P3 (Foxp3) in murine colitis." (PMID 35832651, 2022). "Treg-secreted IL-10 was previously shown to protect mice from spontaneous colitis, and we were concerned that the reduced weight and increased insulin sensitivity in the IL-10fl/fl Foxp3-Cre+ mice were due to colitis." (PMID 33351782, 2021).
colitis (continued). "Rag1-/- mice that received Themis-/- CD4+ Foxp3- T cells were resistant to developing colitis compared to the Rag1-/- mice that received Themis+/+ CD4+ Foxp3- T cells, as measured by increased body weight." (PMID 33177694, 2021). "The specific ablation of RORγt in Foxp3+ Tregs was sufficient to exacerbate 2,4,6-Trinitrobenzenesulfonic acid (TNBS)-induced colitis driven by pathogenic Th1 and Th17 cells but also the Th2-driven pathology of oxazolone-induced colitis." (PMID 33531385, 2021). "In this study, we showed that treatment with rTsPmy significantly increased GATA3 expression in Foxp3+ Tregs in cLP of mice with colitis." (PMID 34336843, 2021). "Having said that, it has also been reported that CD40/CD80/CD86-knock down DCreg also induce the differentiation of Foxp3+ Treg in a murine colitis model, but that this treatment is successful in preventing leukocyte infiltration and disease development." (PMID 33777019, 2021). "Approximately 30% of Treg cells lost Foxp3 expression after colitis induction, indicating that efficient IL-2R signaling is required for sustained Foxp3 expression and suppressive function under inflammatory conditions." (PMID 33408345, 2021). "Administration of IL-33 inhibited the development of T cell transfer colitis by the expansion of FOXP3+ Tregs." (PMID 34759844, 2021). "ET, after injection with OVA TCR enriched T cells derived from Foxp3-DTR mice, prevented weight loss, decreased colonic inflammatory cytokine production, and histological colitis." (PMID 33717186, 2021). "Strikingly, the exacerbated intestinal inflammatory response observed in Lgals1−/− mice was alleviated by adoptive transfer of wild type Foxp3+CD4+ regulatory T cells at induction of colitis." (PMID 34262567, 2021). "In contrast to RORγt, expression of FoxP3 as a marker for Treg cells was decreased in mice with DSS-induced colitis." (PMID 33668818, 2021). "Using mouse models of EAE and colitis we show that loss of RORα affected the expression of IL-17A, RORγt, as well as the frequency of CD25+Foxp3+ Tregs in vivo." (PMID 33397953, 2021). "Transfer of TCRγδ +LAP+ cells ameliorate both colitis induced by the transfer of CD4+ CD45RBhigh cells to immunodeficient mice (a rodent model for Crohn’s disease) and DSS-induced colitis by expanding Foxp3+ Treg cells." (PMID 35919733, 2021). "Taken together, these results suggest that treatment with rTsPmy up-regulates GATA3 expression in Foxp3+ Tregs in the Th2 environment, possibly enhancing the stability of Tregs in cLP of mice with colitis." (PMID 34336843, 2021). "Depletion of Foxp3+ Tregs during IL-33 treatment in DSS colitis ameliorated the positive effect on the intestinal pathology." (PMID 34335571, 2021). "Another study also showed that administration of IL-33 ameliorated TNBS colitis through the downregulation and upregulation of Th1 and FOXP3+ Treg responses, respectively." (PMID 34759844, 2021). "STAT5 also plays a crucial role in IL-2 dependent forkhead box P3 (FOXP3) induction in Treg cells that can prevent intestinal inflammation in experimental colitis." (PMID 34068714, 2021). "Strikingly, overexpression of claudin 2 in transgenic mice and in a colonic epithelial cell line showed that claudin 2 offers protection against DSS-induced colitis and also altered the proportion of FOXP3+ regulatory T cells in injured colonic tissue." (PMID 33673239, 2021). "DSS induced colitis in mice showings pontaneous depletion of Foxp3+ Tregs leading to an increase in the disease severity." (PMID 34440615, 2021). "In some other reports, HIF-1α induces Foxp3 and drives the generation and function of Tregs indicating that HIF-1α-deficient Tregs fail to control T-cell-mediated colitis." (PMID 33519819, 2020). "In mice, macrophages are considered one of the most important sources of IL-10 to maintain and minimize mucosal immunopathology by promoting Foxp3 expression in regulatory T cells (Treg) and their function during colitis." (PMID 32033338, 2020).
colitis (continued). "It was found that a statistically high level of FOXP3 protein was expressed in the colon of the colitis + TOE group." (PMID 33092149, 2020). "In a DSS-induced colitis mice model, expression of PGE2 by AdSCs upregulated the expression of FOXP3+ Treg cells within the inflamed colonic tissue, which further dampened the inflammation and resolved the colitis injuries." (PMID 33287220, 2020). "Previous studies have reported that TGF-β plays a role in inhibiting activated immunity by inducing FoxP3+ regulatory t cells in an inflammatory environment and has been shown to play an important role in relieving inflammation in colitis models." (PMID 32040478, 2020). "In a recent work on a rat colitis model, it was demonstrated that the immunoregulatory impacts of locally injected MSCs from adipose results in a recovered expression of Foxp3 and IL-10 mRNA levels in mesenteric lymph nodes." (PMID 32256612, 2020). "Foxp3+ Treg populations were increased in the lamina propria of inflamed colon under DSS colitis, and although CG-598 treatment slightly increased Treg populations, it was not significantly different compared to that of the vehicle-treated group." (PMID 33519819, 2020). "CD4+Foxp3+Treg cells play a major role in immune homeostasis, and their expression is decreased in colitis mice." (PMID 32581849, 2020). "Mice with OGT deficiency either in IEC or Treg cells exhibited severe intestinal inflammation, indicating that OGT-modulated and Foxp3-based O-GlcNAcylation can regulate the development of colitis." (PMID 32369982, 2020). "Administration of the MSC-DCs in DSS-induced colitis mice causes colon tissue IL-6, IFN-γ, and TNF-α to decrease while Foxp3, IL-10, and TGF-β increase." (PMID 32256612, 2020). "The mRNA and protein expression of Foxp3 in colonic tissue was significantly reduced in the experimental colitis mice compared with the control mice." (PMID 32967687, 2020). "Both QCHS and QCHS-treated DCs improved colonic histopathology, diminished Th17 cell differentiation and inhibited IL-17 production while promoting CD4+CD25+Foxp3+ Treg differentiation and augmenting IL-10 and Foxp3 expression in colitis mice." (PMID 32967687, 2020). "Consistently, the cellularity of CD14+moDC is diminished in mice with MyD88-deficient TECs, in which the frequency and functionality of thymic CD25+Foxp3+ Tregs are decreased, leading to aggravated mouse experimental colitis." (PMID 32398640, 2020). "Tregs, especially CD4+FOXP3+ regulatory T cells, in mouse models of colitis and allergic diarrhea can be induced by Clostridium XIVa from human microbiota." (PMID 33225985, 2020). "Injection of QCHS-treated DCs significantly upregulated the mRNA and protein expression of Foxp3 in colonic tissue samples compared with that in the TNBS-induced colitis group." (PMID 32967687, 2020). "A variety of genera can reduce the immune checkpoint inhibitor-induced colitis possibly by limiting the inflammation through expansion of CD4+/FoxP3+ T reg cells and/or production of anti-inflammatory cytokines." (PMID 32793150, 2020). "The frequency of CD4+CD25+Foxp3+ Tregs was reduced in the experimental colitis model, however the administration of QCHS (3, 6 and 12 g/kg) or SASP markedly upregulated this percentage in the colitis model mice." (PMID 32967687, 2020). "The upregulated expression of FOXP3+ Treg cells within the inflamed colonic tissue dampened the inflammation to resolve the colitis." (PMID 32256612, 2020). "QCHS also reduces the maturation of DCs and IL-17 levels in UC and upregulates the expression of Foxp3 in experimental colitis mice to promote Treg formation." (PMID 32967687, 2020). "Numbers of CD25+Foxp3+ Tregs in spleen and MLNs, especially the latter, which are major lymph nodes draining from the gut, of mice with colitis treated by hUCB-MSC were significantly increased, than untreated mice with colitis." (PMID 33330503, 2020).
colitis (continued). "CD4+ T cell subsets in the colitis tissues were identified using qPCR—T-bet and Ifn-γ for Th1, Gata-3 and Il-4 for Th2, Rorγt and Il-17 for Th17, and Foxp3 and Il-10 for Treg subsets." (PMID 33092149, 2020). "BMSC delivery through an IP route in a DSS-induced colitis mice model revealed higher proliferation of Ki-67 and FoxP3(+) cells, more BMSC migration to inflamed tissue, and an optimal mice colitis recovery in comparison to other routes of cell delivery." (PMID 33287220, 2020). "Specifically, in mice with MyD88-deficient TECs, the frequency and functionality of thymic CD25+Foxp3+ Tregs was decreased and unable to prevent T cell induced colitis." (PMID 32398640, 2020). "Blocking class IIa HDACs attenuates Treg function following HDAC5 and 7 inhibition in CAT and positive and negative selection in the thymus, whereas blocked HDAC9 enhances Treg function by Foxp3 stabilization in a colitis model." (PMID 32235291, 2020). "The RORγt/FoxP3+ T reg cells in the colon are important for the maintenance of GI homeostasis and to prevent the development of colitis." (PMID 31417552, 2019). "We have previously demonstrated that IL-33 ameliorates experimental colitis through promoting Th2/Foxp3+ Treg responses in mice." (PMID 30651971, 2019). "Studies from our lab have shown that TCDD attenuates colitis in mice by suppressing the expression of IL-17 while promoting that of FoxP3 through epigenetic modifications." (PMID 31681214, 2019). "Quantitative RT-PCR showed that DHA significantly reduced expression levels of the transcription factors PU.1 (Th9) and AHR (Th22) and increased levels of Foxp3 (Treg) in the OXA colitis model." (PMID 31284478, 2019). "Previous reports showed that intermittent depletion of Foxp3+ Tregs aggravates intestinal inflammatory responses in acute DSS colitis and in the transfer model." (PMID 31296924, 2019). "IL-10 secreted by lamina propria macrophages has been shown to be important for maintaining Foxp3 expression in a mouse model of colitis." (PMID 30987344, 2019). "Early vitamin D status shapes the microbiota to optimize the population of colonic RORγt/FoxP3+ T reg cells important for resistance to colitis." (PMID 31417552, 2019). "Our data confirms and extends these findings by showing that administration of IL-2/JES6-1 immunocomplexes at the time of initiating DSS treatment is sufficient to expand colonic Foxp3+ Tregs and ameliorate colitis." (PMID 30930900, 2019). "CD4+FoxP3+ regulatory T cells (Tregs), in addition to Th1 and Th17 cells, also play an important role in development of colitis." (PMID 31805144, 2019). "A significant reduction in Foxp3+ Treg in DSS colitis group (1.33 ± 0.27) was shown compared with the control group (2.44 ± 0.31)." (PMID 31836772, 2019). "In MLNs, a significant higher percentage of CD4+Foxp3+ Tregs was observed within the lymphocyte gate already in the acute colitis phase (p < 0.001)." (PMID 31296924, 2019). "In contrast to Th17 and Th1, regulatory T cells (Treg), which can be defined by expression of Foxp3, are capable of suppressing the activation of Th17 and Th1 cells through the production of IL-10 and transforming growth factor-β in mouse colitis models." (PMID 31921214, 2019). "To determine the role of Tregs in the immunomodulation caused by rBmaCys treatment in DSS-induced colitis mice, we analyzed the percent frequency of CD3+CD4+CD25+FoxP3+ Tregs in the colon, spleen, and mesenteric lymph nodes (MLNs)." (PMID 31683524, 2019). "RORγt/FoxP3+ T reg cells from the colon were better suppressors of colitis than splenic CD25+ T reg cells in the T cell transfer colitis model." (PMID 31417552, 2019). "Similar results have been observed in the T cell transfer model, where intact DR3 signaling and a low level of TL1A expression on Foxp3+ regulatory T cells was required to maintain their suppressive function and rescue from colitis." (PMID 30972074, 2019).